RWDD4 (RWD domain containing 4)
Synonyms: FAM28A; RWDD4A; MGC10198
Tractability: PROTAC: ubiquitination databases record sites on it; its protein half-life has been measured.
Gene: Protein-coding gene on chromosome 4 (183,639,635 to 183,659,203, reverse strand). Ensembl gene ENSG00000182552.
Subcellular location (Human Protein Atlas): Intermediate filaments
Gene Ontology:
Molecular function: protein binding
Genetic constraint (gnomAD): Loss-of-function variants: 13 observed, 16.49 expected, observed/expected ratio (o/e) 0.79, 90% interval 0.51 to 1.25. The upper end of that interval is the gene's LOEUF score, 1.25, which puts it in group 5 of 6, group 1 being the genes least tolerant of losing a copy. Missense variants: 121 observed, 135.84 expected, observed/expected ratio (o/e) 0.89, 90% interval 0.77 to 1.04. Synonymous variants: 35 observed, 44.45 expected, observed/expected ratio (o/e) 0.79, 90% interval 0.6 to 1.04.
Homologues: Orthologues: chimpanzee RWDD4 (100% identical), macaque RWDD4 (98% identical), pig RWDD4 (97% identical), dog RWDD4 (95% identical), rabbit RWDD4 (94% identical), rat Rwdd4 (91% identical), mouse Rwdd4a (91% identical), tropical clawed frog rwdd4 (71% identical), zebrafish rwdd (64% identical), Drosophila melanogaster CG10343 (49% identical).
Diseases named in the same sentence as RWDD4 in open-access papers:
RWDD4 is named in the same sentence as 1 disease in open-access papers, as found by Europe PMC text mining. Sharing a sentence is not in itself a finding about the gene and the disease. The quoted sentences say what the papers report.
tumor (1 paper, 2020). "The results of RT-PCR analysis as well as bioinformatics analysis consistently demonstrated that the expression of RWDD4, SDHC, SEPT7, and SFN was downregulated in the tumor tissues as compared with that in adjacent non-tumor tissues." (PMID 32156290, 2020).